IL13 (interleukin 13)
Diseases named in the same sentence as IL13 in open-access papers (continued):
Sharing a sentence is not in itself a finding about the gene and the disease.
asthma (continued). "Interestingly, when examining broncoalveolar lavage of children with asthma, while markers such as IL-13 and IL-6 can differentiate asthmatics from controls, and other cytokines can distinguish moderate from severe asthma, severe asthma itself does not have a clearly TH1 or TH2 inflammatory pattern." (PMID 27980705, 2016). "Nevertheless, Th2 cytokines expression levels (IL-4, IL-5 and IL-13) and miRNA expression profile were similar in AR patients with and without asthma, suggesting that concomitant asthma might have a minor impact on the inflammatory profile and miRNA expression of AR patients." (PMID 27187364, 2016). "However the fact that IL-13, like IL-5, is not increased in non eosinophilic asthma indicates that these Th2 cytokines are essentially related to a peculiar inflammatory profile rather than to asthma itself." (PMID 23555579, 2013). "This supports a potentiating effect of LTD4 on the expression of eotaxin-3 induced by IL-13 in human primary bronchial epithelial cells and suggests that both IL-13 and LTD4 participate in the accumulation of eotaxin-3 in the lungs, which might be relevant in the physiopathology of asthma." (PMID 22952702, 2012). "For CD3+CD28-stimulated accumulation of IL-13+ T cells, there was a significant difference between male and female subjects overall (p = 0.0001) and within asthmatic (p < 0.01) and control (p < 0.03) populations, but not between asthma and control populations within the same gender." (PMID 20667106, 2010). "In addition we have shown for the first time that IL-13 expression in eosinophils was not different between subjects with asthma and EB, although there was a non-significant trend towards increased expression in eosinophils in the disease groups compared to controls." (PMID 19602238, 2009). "If a patient has severe asthma or did not benefit from ICS medications, further treatments including biological agents which act on IL-5 (mepolizumab, reslizumab), IL-4/IL-13 (dupilumab) or IgE (omalizumab) can be used." (PMID 40662069, 2025). "Human BECs from healthy and asthma donors were cultured at the air–liquid interface (ALI) and stimulated with IL-4 and IL-13, acutely or chronically, with or without IL-4Rα mAb, followed by rhinovirus (RV) infection." (PMID 40370530, 2025). "As for the Th2 biomarkers(IL-4 P=0.142, IL-5 P=0.4791, IL-13 P=0.6885, Serum IgE P=0.2534, TARC P=0.2074, TSLP P=0.6571), there are no significant statistical differences observed between asthma and control subjects." (PMID 40503233, 2025). "One study found significantly increased IL-13 in BALF, lung block biopsy specimens, and sputum of asthmatics; however, further differentiation of asthma subtypes revealed that IL-13 was not increased in non-eosinophilic asthma." (PMID 38218943, 2024). "One possibility could be that, even though pro-inflammatory cytokines (IL-4, IL-13, IFNα, IFNγ, IL-17) upregulate many genes in epithelial cells (684–2,876 at 5% FDR in our analyses), they do not significantly interact with polygenic risk factors for asthma in epithelial cells." (PMID 39197446, 2024). "Cases with asthma complicated by ECRS have higher serum periostin concentrations than cases with asthma without ECRS, suggesting the involvement of IL-4/IL-13 in the pathogenesis of ECRS in asthma cases." (PMID 38785953, 2024). "On the contrary, CPX increased the expression of MHCII, CD40L, Il-13, eotaxin (Ccl11), Mbp, and Epo on late reaction; therefore, CPX did not significantly decrease the entire asthma pathway." (PMID 36934237, 2023). "Furthermore, IL-13-induced periostin upregulation established serum periostin as a probable biomarker of the response to anti-IL13 agents (lebrikizumab, tralokinumab) during clinical trials, although later on, serum periostin levels were considered to be not specific for severe asthma inflammation." (PMID 35887589, 2022).
asthma (continued). "Probiotic and prebiotic treatments reduced the levels of Th2 cytokines (IL-4, IL-5, IL-13, IL-17, IL-25, and IL-33) and increased IFN-γ level in the BALF of asthmatic mice as compared to the non-treated asthma group." (PMID 35296330, 2022). "Several lines of evidence support the contention that IL13, and not IL4, controls mucus production in asthma." (PMID 34305924, 2021). "Other biologics targeting type 2 immunity, such as anti-IL-4Rα (targeting both IL-4 and IL-13, dupilumab) or anti-TSLP (tezepelumab), are to date in phase II or III trials in type-2- and non-type-2-immunity-driven asthma." (PMID 32296705, 2020). "Since only IL-13 (but not IL-4 or IL-5) expression was diminished in Cd2−/− HDME mice, our data demonstrate a specific regulation of IL-13 by CD2 in asthma." (PMID 32477356, 2020). "Asthma endotypes are often clustered TH2 high or TH2 low, based on the presence or absence of eosinophils and IL-4, IL-5 and IL-13 cytokines in BAL, all of which we found increased following HDM challenge." (PMID 32038643, 2019). "Moreover, those patients with severe nonatopic asthma (including those with high FeNO as a marker of IL-13 inflammation, high eosinophils, and periostin), uncontrolled besides optimal nonpharmacological and pharmacological treatment, may benefit from omalizumab therapy." (PMID 30310816, 2018). "We show herein that in those with asthma, ST2+ILC are in fact the main IL-13 producers, rather than conventional T-cells." (PMID 30174671, 2018). "ITLN-1 mRNA expression and protein were measured with or without IL-13 stimulation (10 ng/mL) in primary human BEC derived from both ST and SN-Asthma cultured in ALI." (PMID 28775743, 2017). "However, it has been shown that IL-13 inhibits ciliated cell differentiation independent of Notch signaling, suggesting 2 distinct signaling pathways can affect ciliated cell differentiation, which might be of relevance in the different SCs of severe asthma." (PMID 28583446, 2017). "Recently, children (5–17 years) with severe therapy-resistant asthma had significantly increased BAL eosinophils compared control subjects but no increase in BAL fluid interleukin (IL)-4, IL-5, or IL-13 levels." (PMID 25905006, 2014). "In contrast, Th2 cytokines (IL-4, IL-5, and IL-13) are not elevated, suggesting that AHR in this model is not Th2-mediated, contrary to AHR in asthma models." (PMID 24844383, 2014). "In the acute asthma model, we found a 55% reduction in IL-4 transcripts in the OVA-treated sPLA2-X knockout mice but no decrease in IL-5 or IL-13 transcripts." (PMID 23451035, 2013). "Before the advent of genome-wide association studies (GWAS), ADAM33, ADRB2, CD14, MS4A2 (alias FCER1B), IL13, IL4, IL4R, and TNF constituted the most replicated non-HLA candidate genes with asthma and related traits." (PMID 24039878, 2013). "Treatment of established asthma with rapamycin, however, did not significantly alter the HDM-induced increases in lung mRNA levels of IL-4, IL-13 and IL-17A." (PMID 22685525, 2012). "For other asthma-relevant genes such as TNF, IL-4, IL-10, CCL12 (MCP-5), CCL5 (RANTES), and CCR3, there were no significant IL-13-inducible or statin effects on gene expression." (PMID 22583375, 2012). "In the present study, we provided evidence that increased frequency of CD4+/IL-13+, but not CD4+/IL-4+ T cells was correlated with severity of asthma and these findings further suggest that IL-13 is a principal cytokine responsible for asthmatic symptoms." (PMID 21197090, 2010). "Using flow cytometric assay of the whole blood from children with asthma, we demonstrated significantly higher frequencies of both CD4+ and CD8+T cells expressing IL-4 and IL-13 compared with blood obtained from healthy, nonatopic children." (PMID 21197090, 2010). "Because a Th2 cytokine milieu exists in both asthma and COPD, it is important to determine if β2-agonists in the presence of a Th2 cytokine such as IL-13 function as efficiently as in the absence of a Th2 cytokine." (PMID 20470412, 2010).
asthma (continued). "On the other hand an increase in IL-10 and IL-13 in the CD4+, but not in the CD8+ T cells, was related with duration of asthma." (PMID 21197090, 2010). "Our data support the existing evidence that anti-IL-13 mAb are effective in reducing AHR to inhaled spasmogens in preclinical models, but not AHR to inhaled spasmogens in asthma patients treated therapeutically." (PMID 20957211, 2010). "Over expression of IL-13 in sputum, bronchial submucosa and co-localisation to mast cells in the ASM-bundle are features of asthma that are not shared by EB and have therefore further supported its role in the pathogenesis of AHR." (PMID 19602238, 2009). "In an ovalbumin (OVA)-induced asthma model, conditional deletion of Mpc2-but not Ldha-in club cells impaired club-to-goblet cell differentiation, reduced CLCA3 and Foxa3 expression, and attenuated eosinophilic inflammation and Il-13 expression." (PMID 41418787, 2025). "Reduced IL-13 secretion from TH2 cells, however, does not always lead to an alleviation of asthma." (PMID 35697721, 2022). "Moreover, antibodies against IL-13 and IL-17, named tralokinumab (CAT-354) and CNTO 6785, respectively, did not improve asthma outcomes or reduce COPD exacerbations when used alone." (PMID 35806353, 2022). "Furthermore, conjugate vaccines against IL4 failed to reduce mucus production in murine model of asthma induced by HDM, as opposed to ones directed against IL13 that abrogated mucus production in the lung bronchial epithelium." (PMID 34305924, 2021). "However, simple exposure to 1 μg LPS without asthma induction (LPS/PBS) did not significantly affect Foxp3, GATA3, or ROR-γt mRNA levels nor IL-10, TGF-β, IL-4, IL-5, IL-13, or IL-17 levels (p > 0.05) compared to those of Control mice." (PMID 33072079, 2020). "An anti-IL-13 antibody, lebrikizumab, has been shown to improve FEV1 (forced expiratory volume measured during the first second) and reduce IL-13-related biomarkers in clinical trials, but has not consistently shown reduction of asthma exacerbations." (PMID 30616547, 2019). "Because IL-13R (type II IL-4R) mediates the effects of IL-13 on structural (non-hematopoietic) cells, the clinical efficacy of a number of antibodies directed against IL-13 (IMA-638, IMA-026) has been evaluated in asthma." (PMID 28721208, 2017). "While the importance of the Th2 cytokine IL-13 as a central mediator of airway hyperreactivity (AHR) has been described in allergic protein-induced asthma, this has never been investigated in chemical-induced asthma." (PMID 28704401, 2017). "The observation that CS markedly reduces IL‐13‐induced CLCA1 and POSTN expression, which does not recover after CS cessation, is an important finding for biomarker‐guided therapy in asthma since especially periostin is considered as an emerging biomarker for Th2 inflammation." (PMID 28701525, 2017). "There was no change in IL-13 levels or numbers of mucus-producing cells, suggesting a novel and critical role of TLR7 signalling in RV-induced asthma exacerbation." (PMID 26108570, 2015). "Although we show that unstimulated asthma derived cells have similar tenascin-C gene expression to normal ASM, the Th2 cytokine IL-13, can strongly induce tenascin-C expression by ASM suggesting the asthma phenotype may induce ASM to synthesise tenascin-C." (PMID 24587395, 2014). "Unfortunately, whether AHR and airway inflammation as cardinal features of asthma are modulated by TDAG8 in vivo has not been examined; however, it is noted that IL-13 production, which plays a role in these processes, was not affected by TDAG8 deficiency." (PMID 25197168, 2014). "In our data, we could not find interactive effects between IL-13 and ETS exposure at home in asthma phenotypes." (PMID 23382814, 2013). "Notably, si372 treatment also attenuated the ability of IL-13 to up-regulate CCL26 mRNA expression in primary NEC cultures, again irrespective of donor asthma status." (PMID 23402658, 2013).
asthma (continued). "However, in PBMCs from asthma patients the increase in IFNγ correlated significantly with IL-2 (ρ = 0.648 p<0.05), but not with IL4 or IL-13, showing a Th1 dominant shift in response to sitostanol." (PMID 23091602, 2012). "Interestingly, increased accumulation of IL-13+ T cells under CD3+CD28-stimulatory conditions was also observed in females, but was in this case independent of asthma status." (PMID 20667106, 2010). "The finding of an interaction between IL13 and ETS in the present study suggests that negative reports for the effect of a candidate gene for IL13 and asthma, could be explained by a failure to take into account environmental exposures." (PMID 18186920, 2008). "Since we do not detect genotype-specific differences in mRNA degradation of IL-4 or IL-13 in polyclonally stimulated CD4+ T cells and no degradation of IL-5 mRNA, modulation of mRNA stability by KSRP does not appear to be the main reason for the effects observed in our asthma model." (PMID 40095032, 2025). "We tested this hypothesis by comparing plasma cytokines, including IL-2, IL-5, IL-10, IL-13, IL-17A, IL-22, IL-33, IFN-γ, and TNF-α and the adipokine, leptin in normal weight and overweight/obese children, both with and without asthma in a cross-sectional study." (PMID 39902293, 2024). "Interestingly, even though levels of IL-5 and IL-13 were increased in the media of ILC2 culture from Hps1−/− mice, levels of eosinophilia and eotaxin expression were comparable, and no asthma-related phenotypes were observed in these mice after bleomycin challenges." (PMID 39405112, 2024). "Under these conditions, CD8-depleted PBMCs from the patients with SR asthma produced significantly increased mean concentrations of both IL-17A and IFN-γ compared with the those seen in the patients with SS asthma, although the mean production of IL-10 and IL-13 did not significantly differ." (PMID 25772594, 2015).
Allergy (406 papers, 2006 to 2026). An allergy is an immune response or reaction to substances that are usually not harmful. "Other genes, including CD14, FOXP3, STAT6, SPINK5, IL-10 and IL-13, have demonstrated polymorphisms that affect allergy prevalence as well." (PMID 40004029, 2025). "Elevated levels of IL-4 and IL-9 suggest a Th2 profile of the inflammatory response associated with allergy and IL-13 response." (PMID 41239983, 2025). "IL4R rs1801275 AA, IL13 rs20541 GG, and IL-4 rs2243250 CC genotypes synergistically amplified allergy risk under vitamin D deficiency (adjusted OR = 26.14, p = 0.019; OR = 6.51, p = 0.025; OR = 4.13, p = 0.007)." (PMID 40927566, 2025). "Elevated levels of IL‐4 and IL‐13 are often associated with allergic reactions and are observed in children with AH accompanied by AR." (PMID 38572767, 2025). "ANO1, which is associated with allergy and itch signaling, was also upregulated with IL-13 treatment [log2 (fold change) of 2.45]." (PMID 38344408, 2024). "In particular, IL-4 rs2243250, IL-4R rs1801275, and IL-13 rs1800925 variants, affecting expression and/or functionality of the gene products were considered markers of predisposition to allergy." (PMID 39202464, 2024). "Th2 cytokines, such as IL-4, IL-5 and IL-13, have a number of effects associated with allergy, including IgE class-switching by B cells, eosinophil activation and recruitment, and mucus production." (PMID 40115160, 2024). "IL-13 is mainly secreted by Th2 cells but also can be secreted by mast cells, and is frequently linked to Th2 cell-related immune responses including allergic diseases, the IgE response, and parasitic infections." (PMID 37400766, 2023). "The roles of IL-4 and IL-13 in facilitating the isotype switching of antibodies to IgE point towards their association with allergic reactions." (PMID 38097754, 2023). "Consistent with this, studies showed that cytokine variants including TNF-α 308 A → G, IL-13 and IL-4RA as well as genetic variation in IgE receptor were associated with predisposition to drug-induced allergy." (PMID 35307016, 2022). "The IL-13 gene is located on the 5q31 chromosome, which also encodes other factors involved in allergy mechanisms such as IgE, IL-4, IL-3, and IL-5." (PMID 35629280, 2022). "The previous investigations have shown the essential oil immunostimulatory effects on T cells and meaningfully inhibited allergy-associated cytokines IL-4 and IL-13." (PMID 36518853, 2022). "Subgroup analyses showed that higher Il-4 and Il-13 transcripts in cord blood CD4+ T-cells were associated with an increased risk of allergic diseases in children of the HC group." (PMID 35745240, 2022). "Th2 response up-regulates the expression of IL-4, IL-5, and IL-13, which are essential for allergic diseases caused by the pathogenic infection." (PMID 36119076, 2022). "Recently, several studies have found that polymorphisms in the IL-13 and IL-4 genes are often associated with an increased risk of allergic diseases, including atopic dermatitis, allergic rhinitis, and bronchial asthma." (PMID 35629280, 2022). "On the one hand, IL-25 activates type 2 immunity via the relevant cytokines, including IL-4, IL-5, and IL-13, which are associated with the development of pathogenic infection-related allergic diseases." (PMID 36119076, 2022). "Many similarities exist between IgG4-RD and allergic diseases, such as the increase of eosinophil counts, IgE, IgG4, and Th2 associated cytokines (IL-4, IL-5, and IL-13)." (PMID 35432312, 2022). "The IL-4 and IL-13 cytokines produce IgE through increased secretion and action of B cells, which differentiates Th2 cells and causes allergic reactions." (PMID 35889810, 2022). "Next, we assessed the levels of IgE and IL13, commonly used as clinical diagnostic biomarkers of allergy, in serum from the different mouse cohorts." (PMID 33942458, 2021).